MMP1 (matrix metallopeptidase 1)
Diseases named in the same sentence as MMP1 in open-access papers (continued):
Sharing a sentence is not in itself a finding about the gene and the disease.
colon carcinoma (continued). "To explore the role of MMP1 in the proliferation of colon cancer cells facilitated by TAMs, we constructed MMP1-shRNA or MMP1-overexpressing lentivirus and transfected them into TAMs or U937 cells, respectively." (PMID 34753916, 2021). "In this study, we demonstrated that MMP1 derived from TAMs markedly facilitated colon cancer cell proliferation via accelerating cell cycle transition from G0/G1 to S and G2/M phase." (PMID 34753916, 2021). "This is in concordance with clinical data of MMP-1 overexpression correlating strongly with advanced tumor stage, metastatic progression and adverse outcomes in colon cancer." (PMID 34203220, 2021). "Simultaneous activation of PKC/p38 and EGFR/ERK signaling potentiates MMP-1 gene and protein expression, and augments colon cancer cell invasion while blocking MMP-1 activity abolishes M3R agonist-induced colon cancer cell invasion." (PMID 34203220, 2021). "MMP1 belongs to the type of collagenases, which was found to be closely related to lung squamous cell carcinoma and colon cancer in previous studies." (PMID 35069702, 2021). "To further elucidate the potential mechanism of MMP1-induced proliferation of colon cancer cells, we examined the expression of several cell cycle-related genes by RT-PCR and western blotting analysis." (PMID 34753916, 2021). "Additional studies showed that ACh-induced MMP1 expression and colon cancer cell invasion can be abolished by pre-treatment with inhibitors of muscarinic receptor or MMP1 activation." (PMID 34884958, 2021). "Altogether, these findings suggested that MMP1/PAR1 axis facilitates the proliferation of colon cancer cells through MAPK/Erk signaling." (PMID 34753916, 2021). "As a consequence of its ability to degrade ECM, MMP1, a collagenase, is a key player in colon cancer cell migration and metastasis, and its expression in human CRC is also associated with cancer progression, metastasis, and a poor prognosis." (PMID 33450835, 2021). "The level of MMP1 strongly correlates with advanced colon cancer, metastatic dissemination, and an adverse outcome." (PMID 34753916, 2021). "Since Fra-1 regulates the expression of many genes involved in tumor invasion, especially MMP-1 expression in breast, osteosarcoma, and colon cancers, targeting Fra-1 seems to be a promising strategy for treatment of mCRC." (PMID 31947604, 2020). "We thus further analyzed the data from TCGA and showed that HPSE is positively correlated with the expression of MMP1 in colon cancer (r = 0.3476, p < 0.0001) and rectal cancer (r = 0.3428, p < 0.0001), but not MMP7, MMP10, and MMP13." (PMID 31001480, 2019). "The results of this analysis confirmed that the proximal MMP-1 promoter containing the GAS-like SBE was inducible by IL-6 in SW480 (1.2-fold) colon cancer cells, under conditions of low (1%) serum." (PMID 28819304, 2017). "In human colon cancer cells, M3R activation induces a 30- to 50-fold increase in the levels of MMP1 mRNA expression, an action that appears critical for colon cancer cell invasion." (PMID 28416748, 2017). "It was reported that Hes1 activates signal transducers and activators of the transcription 3 (STAT3) pathway, and that STAT3 controls MMP1 expression in colon cancer cells." (PMID 26650241, 2015). "By transfecting miR-34a into human colon cancer cells, the expression of both MMP-1 and MMP-9 was decreased substantially and ultimately led to inhibition of human colon cancer cell migration and invasion." (PMID 24518611, 2014). "In two different colon cancer cell lines, muscarinic receptor activation was also shown to stimulate ~50-fold increase in MMP-1 mRNA expression compared to control." (PMID 24518611, 2014). "PEA3 has been established as an important regulator of cell invasion in colon cancer and gastric adenocarcinoma cells through regulation of MMP-1 and MMP-7 respectively." (PMID 21143918, 2010).
colon carcinoma (continued). "In CRC, MMP1 derived from tumor-associated macrophages promotes the cell cycle transition from G0/G1 to S and G2/M phases, and the overexpression of HOXC6 induces EMT in colon cancer cells." (PMID 38443703, 2024). "MMP-1, -2, -7, -9 and -13 are markers of poor colon cancer prognosis." (PMID 36139106, 2022). "Unlike in AD, high levels of MMP-1 in plasma are associated with a poorer prognosis in colon cancer, as assessed by a multivariate analysis of 5-year survival." (PMID 36362588, 2022). "Meanwhile, this drug reduced the expression of MMP1, 2, and 9 genes in colon cancer cells, which might be related to the decreased invasion and migration ability of tumor cells." (PMID 36147444, 2022). "Combined with these findings, we speculated that MMP1 might accelerate the cell cycle transition of colon cancer cells by regulating cdc25a/CDK4-cyclin D1 and p21/cdc2-cyclin B1 complexes through alteration in the expression of c-Myc and ETV4." (PMID 34753916, 2021). "To validate this hypothesis, we screened DUBs that ubiquitin-dependently control Fra-1 stability, identified USP21 as a Fra-1 DUB, and confirmed that USP21 overexpression enhances the MMP-1 gene expression transcribed by Fra-1 in colon cancer cells." (PMID 31947604, 2020). "In our analysis we did not observe significant association of rs1799750 in MMP-1 with breast, lung and colon cancer risk." (PMID 32765800, 2020). "In the present study we analyzed whether polymorphisms rs28366003 in MT2A, rs1799750 in MMP-1, rs243865 in MMP-2, rs11568818 in MMP-7 and rs2252070 in MMP-13 genes are associated with the risk of breast, lung or colon cancer among polish subjects." (PMID 32765800, 2020). "Notably, while known ISGs were positively regulated by IFN-γ in colon cancer cell lines, MMP-1, which also contains a GAS-like SBE in its proximal promoter, was down-regulated by IFN-γ." (PMID 28819304, 2017). "Finally, although MMP1 expression was robustly increased in almost all primary colon cancers, we were unable to demonstrate a quantitative relationship between the levels of CHRM3/M3R and MMP1 expression." (PMID 28416748, 2017). "Fifteen genes (DUSP2, INFGR1, IL6, IRF2, JAK2, MAP3K10, MMP1, NFkB1A, NOS2A, PIK3CA, SEPX1, SMAD3, TLR2, TYK2, and VDR) were significantly associated with colon cancer mortality at the <0.05 level; an additional 15 genes had gene PARTP values between 0.05 and 0.10." (PMID 25541970, 2014). "Fifteen genes (DUSP2, INFGR1, IL6, IRF2, JAK2, MAP3K10, MMP1, NFkB1A, NOS2A, PIK3CA, SEPX1, SMAD3, TLR2, TYK2, and VDR) were associated with colon cancer mortality (PARTP <0.05); JAK2 (PARTP = 0.0086), PIK3CA (PARTP = 0.0098), and SMAD3 (PARTP = 0.0059) had the strongest associations." (PMID 25541970, 2014). "In CRC, MMP-1 expression correlates with advanced colon cancer stage and poor prognosis." (PMID 24518611, 2014). "In addition, high plasma MMP1 concentration correlates with a poor colon cancer prognosis." (PMID 38639039, 2024). "Thus, we inferred that TAMs facilitate the proliferation of colon cancer cells, which may be attributed to the paracrine factor including MMP1 secreted by TAMs." (PMID 34753916, 2021). "In addition, MMP1 contributes to the metastatic phenotype of colon cancer cells." (PMID 34753916, 2021). "Furthermore, ablation of BACH1 in human colon carcinoma or in prostate cancer cells prevents cell growth, migration, and invasion in vitro, decreasing the expression of its main metastasis-related genes, MMP1, let-7a, and CXCR4." (PMID 32132179, 2020).
colon carcinoma (continued). "The aim of this study was to investigate association of polymorphisms rs1799750 in MMP-1, rs243865 in MMP-2, rs11568818 in MMP-7, rs2252070 in MMP-13 and rs28366003 in MT2A, together with serum Zn level, with occurrence of breast, lung and colon cancer in Poland." (PMID 32765800, 2020). "Furthermore, kaempferol may play an anti-colon cancer role by regulating the expression of MMP1, MMP2, and MMP9 protein, thereby increasing the expression level of miR-339-5p to mediate PKM alternative splicing reversing aerobic glycolysis in colon cancer cells." (PMID 39221164, 2024). "Acetylcholine increased the expression of matrix metalloproteinase 1 (MMP-1) and stimulated the invasion of HT29 and H508 colon cancer cells into human umbilical vein endothelial cell monolayers." (PMID 37175905, 2023). "The TCM monomer composition (i.e., kaempferol) and target proteins MMP1 (ID : P03956), MMP2 (ID : P08253), and MMP9 (ID : P14780), which had a strong correlation with colon cancer, were screened using HERB database." (PMID 36147444, 2022). "Parasympathetic signaling through acetylcholine promotes matrix metalloproteinase 1 (MMP1) expression, facilitating the invasion of HT29 and H508 human colon cancer cells, which can be rescued by atropine and anti-MMP1 antibody." (PMID 35223829, 2022). "In vitro analyses on colon carcinoma cell lines showed that M3R targeting counteracts acetylcholine-induced p38, ERK1/2 and Akt signaling, and disrupts MMP-1 expression and tumor cell invasion." (PMID 34203220, 2021). "Our study for the first time revealed MMP1 derived from TAMs can activate tumor-expressed PAR1 and thereby facilitate the proliferation of colon cancer cells." (PMID 34753916, 2021). "More interestingly, inhibition of Fra-1 by miR-34a led to downregulation of MMP-1 and MMP-9 in colon cancer cells, and eventually inhibited cell migration and invasion." (PMID 26337460, 2015). "Previously, in human colon cancer cell lines, we showed that of the ~25 known MMP genes, acetylcholine treatment selectively induced robust transcription of MMP1, MMP7 and MMP10." (PMID 23617763, 2013). "In a systematic analysis of MMP gene transcription, we identified the same three MMP genes [MMP1 (functional human homologue of mouse MMP13), MMP7 and MMP10] as target genes for acetylcholine-M3R activation in human colon cancer cell lines." (PMID 23617763, 2013). "The effect of IL-1β and IP6 on the expression of mRNA of MMP-1, MMP-2, MMP-3, MMP-9, MMP-10, and MMP-13 and that of their tissue inhibitors TIMP-1 and TIMP-2 in colon cancer cells using real-time QRT-PCR assay was determined." (PMID 22415590, 2012). "We found the best three single-gene discriminators for colon cancer are MMP7, DPT and MMP1 having 97.5%, 96.3% and 95.1% classification accuracy on the training set, and 97.9% and 90.9%, 97.9% and 74.6%, and 91.7% and 84.1% on the two test sets, respectively." (PMID 21060876, 2010). "have determined that ETV4 can combine with the promoter of MMP1 to activate t its transcription, suggesting that the ETV4-related pathway may serve as a therapeutic target for colon cancer." (PMID 40469297, 2025). "The reduction of MMP-1 and MMP-3 expression was reported to correlate with the inflammatory cytokine IL-6, signal transducer and activator of transcription (STAT), and the AP-1 (IL-6/STAT-1/AP-1) axis in colon cancer." (PMID 36839884, 2023). "Moreover, both in vitro and in vivo studies have shown that blocking the activity of matrix metalloproteinases (MMPs) that are induced selectively by M3R activation, i.e., MMP1 and MMP7, also impedes colon cancer growth and progression." (PMID 33450835, 2021). "All of these results indicated that ETV4 could bind to the P4 fragment of the MMP1 promoter and transcriptionally activate MMP1 in colon cancer cells, which confirmed the MMP1/ETV4/MMP1 positive feedback." (PMID 34753916, 2021).
colon carcinoma (continued). "Five SNPs, rs1799750 in MMP-1, rs243865 in MMP-2, rs11568818 in MMP-7, rs2252070 in MMP-13 and rs28366003 in MT2A has been studied in various cancers including breast, lung and colon cancer, but results were ambiguous." (PMID 32765800, 2020). "To ensure that these findings held true for colon cancer cells (HCT116), we investigated the effect of USP21 on Fra-1 activity by measuring the expression of MMP-1, a target gene of Fra-1 as AP-1 binds to the MMP-1 promoter." (PMID 31947604, 2020). "In a study of cell invasion, ACh and bile acids increased MMP-1 expression and the invasiveness of H508 and HT29 colon cancer cells in Matrigel-based and electrical cell impedance sensing assays; these effects were blocked by pre-treatment with atropine or an anti-MMP-1 neutralizing antibody." (PMID 30841571, 2019). "Notably, MMP-1 (~250-fold, P < 0.01) and IL-6 responsive BCLXL mRNAs were greatly increased after treatment with IL-6 (18 h) in SW480 colon cancer cells under conditions of high (10%) serum." (PMID 28819304, 2017). "We observed that NOS2A, MMP1, and VDR were associated with survival after colon cancer diagnosis and no major angiogenesis genes on our platform were associated with rectal cancer." (PMID 25541970, 2014). "One hint might be the observed cleavage of Laminin5, since this process is in most part mediated by MMP-1 and MMP-7, and only in little part by MMP-9, in colon cancer." (PMID 24913355, 2014). "Colon cancer cell invasion and migration correlated with increased MMP-1 gene expression, and these actions were reversed by chemical inhibitors or neutralizing antibodies against MMP-1." (PMID 24518611, 2014). "However, blockage of PI3K/Akt pathway by AKT inhibitor MK-2206 did not affect the tumor-promoting effect of exogenous MMP1 on colon cancer cells." (PMID 34753916, 2021). "Moreover, this study reported that patients with stage III colon cancer experienced shorter time to distant metastasis and decreased overall survival when lacking MMP-1." (PMID 25483099, 2014). "However, although all the tested colon cancer cell lines were responsive to IFN-γ, as revealed by induction of ISGs14, 15 such as STAT-1, STAT-3, interferon responsive factor (IRF-1), and BCLXL, unexpectedly MMP-1 mRNA levels were reduced following IFN-γ treatment (18 h)." (PMID 28819304, 2017). "For example, MMP1 is a dominant factor for metastasis in MDA-MB-231 cells, but it is not upregulated significantly in UEV1A-overexpressed HCT116 colon cancer cells." (PMID 29662619, 2018). "In this study we have used comparative gene expression analysis and promoter mapping to demonstrate a direct link between IL-6 and MMP expression in colon cancer, via STAT-1 and novel non-canonical SBEs identified in the MMP-1 and MMP-3 proximal promoters." (PMID 28819304, 2017).
liver fibrosis (54 papers, 2009 to 2026). "Several studies have shown an association between reduced serum concentrations of MMP-1 and progression of liver fibrosis." (PMID 36556936, 2022). "The GSE100901 database shows that MMP1 is downregulated and linked to liver fibrosis." (PMID 38905402, 2024). "In the hepatic fibrosis model group, the MMP1/TIMP1 ratio was significantly decreased thus leading to reduced ECM degradation and increased collagen accumulation." (PMID 41293246, 2025). "PZW mitigated hepatic fibrosis, with its effect associated with the inhibition of the IL-6/JAK2/STAT3 and TGF-β/Smad2/3 signaling pathways and through raising the MMP1/TIMP-1 ratio." (PMID 41293246, 2025). "PZW mitigated hepatic fibrosis in association with IL-6/JAK2/STAT3 and TGF-β/Smad2/3 signaling pathway inhibition favoring MMP1/TIMP-1 ratio that attenuated collagen deposition and promoted collagen degradation." (PMID 41293246, 2025). "Recently, an anti-fibrotic activity of MMP1-decorated polymersomes (MMPsomes) has been reported in an in vivo model of hepatic fibrosis." (PMID 39062090, 2024). "In this in vivo study, it is expected that the preventive effect of AHCC on liver fibrosis promotion is partly due to the enhancement of MMP-1 expression." (PMID 39316687, 2024). "Vit-E has also been reported to diminish the expression of genes involved in fibrotic process, such as matrix metalloproteinase-1 (MMP-1), IL-1β, or collagen, and delay the progression of liver fibrosis, radiation-induced fibrosis, and renal fibrosis." (PMID 36012952, 2022). "Previous research has demonstrated that the serum level of MMP-1 tends to decline with the severity of liver fibrosis, inflammation and the disease condition." (PMID 35715541, 2022). "Excessive ECM deposition is known to cause organ fibrosis (e.g., liver fibrosis) and therefore the relationship between MMP-1 and liver fibrosis has recently garnered increasing attention from the scientific community." (PMID 34611503, 2021). "This study suggested that the delivery of MMP-1 is a promising therapeutic approach to attenuate liver fibrosis." (PMID 32414178, 2020). "Further, FAP and MMP‐1 have been shown to be positively correlated with the degree of liver fibrosis in mice." (PMID 32311840, 2020). "Although HCV infection in hepatocytes triggers key fibrotic factors in HSCs, we can show that the YCHD can promote the expression of MMP1, reduce the occurrence of liver fibrosis, and control further progression of hepatitis C infection." (PMID 32050950, 2020). "The overexpression of MMP1 reduces the number of activated hepatic stellate cells (HSCs) that are activated during transient overexpression in the liver and reduces liver fibrosis." (PMID 32050950, 2020). "MMP-1 degrades key collagens in hepatic fibrosis and is a promising marker for antifibrotic therapy." (PMID 32664553, 2020). "In this study, isolated primary rat BMSCs were transfected with a recombinant adenoviral vector containing human MMP-1 gene, and these transfected cells were then transplanted in a carbon tetrachloride (CCl4)-induced rat model of liver fibrosis." (PMID 32414178, 2020). "Similar to our results, recent studies have reported that MMP-1 has anti-fibrotic effects in a liver fibrosis model and a lacerated skeletal muscle model." (PMID 32872523, 2020). "MMP-1 also plays a crucial role in ECM degradation during the recovery phase of experimental liver fibrosis." (PMID 32414178, 2020). "Overexpression of MMP-1 induced by human adenovirus vector expressing MMP-1 (AdMMP-1) injection attenuated liver fibrosis and stimulated hepatocyte proliferation in a rat fibrosis model." (PMID 32664553, 2020). "The components of fibrous collagen are mainly type I collagen in liver fibrosis, which is largely degraded by MMP1 in humans." (PMID 30635047, 2019). "Transplantation of si-MMP-1-transfected IC-2 sheets achieved almost the same reduction in liver fibrosis as si-Ctrl-transfected IC-2 sheets." (PMID 31048740, 2019).